LCN2 (lipocalin 2)
Diseases named in the same sentence as LCN2 in open-access papers (continued):
Sharing a sentence is not in itself a finding about the gene and the disease.
tumor (continued). "Background and objective: Lipocalin 2 (LCN2) has an oncogenic role in promoting tumorigenesis through enhancing tumor cell proliferation and the metastatic potential." (PMID 31151292, 2019). "Another iron regulating protein respectively a siderophore binding protein, Lcn2 was shown to potently increase the intracellular labile iron pool of cancer cells, tumor proliferation and induce chemotherapy resistance." (PMID 31413815, 2019). "Recently, LCN2 was reported to potentially play important roles in tumour progression and chemoresistance in many kinds of cancer." (PMID 31819048, 2019). "The tumour xenograft model showed that vitamin D inhibited the expression of LCN2 in the tumour and enhanced cisplatin sensitivity, while the tumour with high LCN2 expression was not sensitive to cisplatin." (PMID 31819048, 2019). "Different macrophage phenotypes influence Lcn2 expression as they play a pivotal role in the tumor microenvironment due to their diverse functions." (PMID 31413815, 2019). "While the majority of studies so far focused on mechanisms promoted by tumor cell-derived Lcn-2, recent data from our group suggest that stromal Lcn-2 promoted metastasis by enhancing EMT and lymphangiogenesis." (PMID 30641920, 2019). "One transcript, the acute stress response signal Lcn2, was equally increased in R848 and vehicle-treated tumor-bearing animals (P < 0.0001 vs. sham-operated vehicle for both groups)." (PMID 31615993, 2019). "Consistent with previous studies, we found that tumor burden resulted in elevated hepatic Il1b, Ifna, Lcn2, Apcs, Crp, and Orm1." (PMID 31615993, 2019). "The results showed that upon silencing LCN2 expression, tumour growth was inhibited, which was in accordance with the in vitro experiments." (PMID 31819048, 2019). "Once LCN2 was highly expressed, the vitamin D inhibitory effect on LCN2-NF-κB was weakened, and the chemosensitivity of tumour cells was reduced." (PMID 31819048, 2019). "LCN2 was detected in the supernatant of both hNEP and tumor cells, in which hNEP secreted over 10 times amount of LCN2 than the same number of tumor cells, suggesting hNEP as the major source of LCN2 in the tumor microenvironment." (PMID 31500632, 2019). "Lcn2 is upregulated in several types of cancers, and has been shown to facilitate tumor progression." (PMID 31671654, 2019). "At the same time, based on this study, the use of vitamin D is important for the inhibition of LCN2 and other genes, which benefited the sensitisation of tumour cells to chemotherapy." (PMID 31819048, 2019). "Of note, CXCL1 and LCN2 synergistically enhance tumor malignancy, indicated by the profound promotion of DU145 migration that occurs from the stimulation with both cytokines." (PMID 31500632, 2019). "CHI3L1 and LCN2 are strongly produced by tumor cells and TAM, and besides their immunomodulatory function both biomarker proteins have been linked to several tumor-promoting processes such as EMT, (lymph)angiogenesis and matrix remodeling." (PMID 30111338, 2018). "These concomitant events present the tumorigenic and immunological effects of Lcn2, thus facilitating tumor growth and metastasis." (PMID 30591630, 2018). "Apart from Lcn2, Hepcidin is another important factor in the intricate relationship between iron metabolism and tumor microenvironment." (PMID 30591630, 2018). "TAMs can secret Lcn2 and elevate intracellular iron concentration in tumor cells via Lcn2 as transporter." (PMID 30591630, 2018). "Lipocalin-2 (LCN2), which is secreted by adipocytes, neutrophils, macrophages, and tumor cells, is an adipokine expressed in the serum of obese and PDAC patients." (PMID 30366466, 2018). "CHI3L1 and LCN2 levels were subsequently measured in primary tumor lysates and sera from 4T1 + RAW264.7 and 4T1 inoculated mice and showed a progressive increase from 3 to 5 w p.i.." (PMID 30111338, 2018).
tumor (continued). "Macrophage-derived Lcn-2 stimulates cancer cell proliferation, tumor cell dissemination, metastasis, and tumor lymphangiogenesis." (PMID 28979267, 2017). "Conditional gene silencing confirmed the identity of the molecule produced in apoptotic tumor cells, responsible for the induction of LCN2 in macrophages, as the lipid S1P." (PMID 28804221, 2017). "In this regard, we noticed that the high-affinity iron-carrier Lcn-2 is part of the pro-tumor macrophage phenotype and upregulated following macrophage-apoptotic cell interactions." (PMID 28979267, 2017). "Our work revealed that apoptotic tumor cells stimulated protein expression and secretion of Lcn-2 in macrophages along with their functional shift toward an alternative phenotype." (PMID 28979267, 2017). "Increasing evidence indicates that transcription factors, such as IkBz, NF-kB, and ELF3 (E74-like factor 3), play crucial roles in the regulation of LCN2 expression in tumor cells of various origins, including lung and chondrocytes." (PMID 29098164, 2017). "Apart from its role in inducing cell migration, which other cellular processes LCN2 acts on to stimulate tumor growth remains to be elucidated." (PMID 28467300, 2017). "LCN2 displays pleiotropic functions that range from managing endogenous iron demand necessary for tumor cell replication, proliferation, survival, cellular differentiation, and migration, rendering LCN2 a putative mediator of tumor development." (PMID 28804221, 2017). "LCN2, also known as neutrophil gelatinase-associated lipocalin (NGAL), is required for tumor progression and metastasis." (PMID 29285270, 2017). "Functionally, Lipocalin 2 has been suggested in promoting tumorigenesis through enhancing tumor cell survival and proliferation, and metastatic potential." (PMID 28088789, 2017). "Although we do not yet know the direct repressed target genes of TCF7L1 that contribute to skin tumorigenesis, we clearly showed that LCN2 is a major downstream effector of TCF7L1 that drives tumor growth." (PMID 28467300, 2017). "Recent findings highlight a rather underappreciated role of S1P in tumor lymphangiogenesis, referring to the production of interleukin-1β (IL-1β) and lipocalin-2 (LCN2) by a tumor-promoting macrophage phenotype." (PMID 28804221, 2017). "A literature examination of the missing cytokines (IL6, IL8, LCN2, MCP1, and CCL5) indicated that most of them have indeed been implicated in tumor growth, tumor angiogenesis, or tumor invasion." (PMID 26959742, 2016). "This type of pathway is found in tumour cells, and expression of ferroptosis-related genes, such as lipocalin-2 (LCN2), a protein that participates in iron homeostasis and enhances brain iron clearance after ICH, can be tested in ICH." (PMID 27293511, 2016). "ATP1B1, GPC3, KCNIP3, and PRLR transcript levels in tumor tissues were significantly lower in PTCs than in NT, whereas LCN2, LGALS1 and SCD1 expression was upregulated in PTC compared with NT." (PMID 27249794, 2016). "Nevertheless, an involvement of LCN-2 in the promotion of angiogenesis and tumor progression has been also reported." (PMID 27612200, 2016). "Compared with control groups, overexpression of LCN2 promoted tumor growth with remarkably increased tumor volume and weight in nude mice." (PMID 27602760, 2016). "Even though LCN2 is suggested to have a role in the early stages of tumor development or as a prognostic marker, there is an urgent need for elucidating the role of LCN2 by studying its effects on metastasis behavior." (PMID 27729871, 2016). "To verify that the in vitro effects of LCN2 can be replicated in vivo, we created a xenograft tumor model by injecting SCID mice with C33A-LCN2 overexpressing or C33A-control cells." (PMID 26840566, 2016). "LCN-2 was reported to be expressed in neoplastic colon cells and has been found to correlate with tumor stage mainly exhibiting an important anti-inflammatory function." (PMID 27612200, 2016).
tumor (continued). "Western blot and TCGA database analysis also showed that the expression of LCN2 was higher in tumor tissues than in normal epithelial tissues." (PMID 27912767, 2016). "In the immunosuppressive environment of the tumor stroma LCN2 cooperates with CCL2 to induce immunoregulatory DCs and subsequently CD4(+)FoxP3(+) Treg cells and supports metastasis." (PMID 26497994, 2016). "We showed for the first time that the N-myc downstream regulated gene 1 (NDRG1) and NDRG2, known as tumor suppressor genes, are negatively regulated by LCN2 in CCA cells." (PMID 27782193, 2016). "On the basis of its overexpression in human cancers and apparent pro-inflammatory activity and stimulatory effects on tumor growth, LCN2 has been proposed as a therapeutic target for cancer." (PMID 25635769, 2015). "Both LCN2 and TRα displayed similar expression patterns relative to tumor grade, TNM stage, and vascular invasion grade." (PMID 25940797, 2015). "Immunohistochemical staining in their cohort of patients demonstrated that LCN2 expression also increased in various tumor stages." (PMID 25940797, 2015). "In our study, CCL2 orchestrates CCR2-expressing immunomodulatory cells including Tregs, MDSCs and TAMs in the tumor microenvironment, and generates DCregs partly in collaboration with LCN2 that is released from the CCL2-stimulated tumor cells." (PMID 25883937, 2015). "LCN2 is currently one of the most interesting and enigmatic proteins involved in the process of tumor development." (PMID 25940797, 2015). "Both TRα and LCN2 showed similar expression patterns in relation to survival rate, tumor grade, tumor stage and vascular invasion." (PMID 25940797, 2015). "Overexpression of LCN2 enhanced tumor cell migration and invasion, and conversely, its knockdown suppressed migration and invasion, both in vitro and in vivo." (PMID 25940797, 2015). "Under these culture condition, LCN2 mRNA levels increased by 3-fold at 6 h and then decreased at 12 h in B16-F1 cells, indicating that LCN2 was expressed in tumor cells in response to hypoxic stimulation." (PMID 25467539, 2014). "For clinical use of LCN2 as a plasma marker for a hypoxic tumor, it is necessary to combine it with another conventional marker for kidney injury." (PMID 25467539, 2014). "In a tumour milieu LCN2 is potentiated by proinflammatory cytokines Il-1β, TNF-α, and IL-17 and is involved in the epithelial to mesenchymal transition (EMT)." (PMID 25010215, 2014). "In the present study, we identified LCN2 as a plasma marker reflecting hypoxic tumors through gene expression profiling of normoxic and hypoxic tumor tissues." (PMID 25467539, 2014). "Consistent with this, we observed that many macrophages infiltrated hypoxic tumor tissue, and LCN2 expression increased in hypoxic tumor cells." (PMID 25467539, 2014). "DC immunisation was highly efficient: when using WT DCs, LCN2 contributed to an increase in the DCs’ anti-tumour effectiveness by inducing a TH1 microenvironment phenotype." (PMID 25010215, 2014). "In summary, we demonstrated that LCN2 levels increased in tumor cells cultured under hypoxic conditions, at HIF-1α-positive regions of tumors, and in plasma collected from mice bearing hypoxic tumors." (PMID 25467539, 2014). "The plasma levels of lipocalin 2, MMP-9 and the lipocalin 2/MMP-9 complex are associated with more advanced clinical stages and/or tumor sizes in OSCC patients." (PMID 23365550, 2013). "Attenuating LCN2 expression in BxPC3 cells reduced tumor growth (p<0.0001) and increased sensitivity to gemcitabine (p = 0.0003)." (PMID 23056397, 2012). "We have provided strong evidence that LCN2 promotes attachment, invasion, tumor growth, and gemcitabine resistance in multiple PDAC cell lines." (PMID 23056397, 2012). "In this study, enhancing LCN2 expression in PANC1 cells markedly increased tumor growth, whereas suppressing its expression in BxPC3 cells reduced tumor growth rate." (PMID 23056397, 2012).
tumor (continued). "It is possible that the growth potential of the tumor cells and their propensity for metastasis in our model is so strong that it overrides a modulating effect of lipocalin-2." (PMID 22737251, 2012). "While forced LCN2 expression in MiaPaca2 decreased tumour size, metastatic spread, VEGF expression, and microvascular density." (PMID 23056397, 2012). "We therefore expected the level of lipocalin-2 in plasma to increase with increasing tumor burden as a result of secretion both from the tumors and from the liver." (PMID 22737251, 2012). "Another mechanism by which lipocalin-2 can convey a metastatic potential to tumor cells has been proposed to relate to the possible activating or stabilizing effect of lipocalin-2 on MMP-9." (PMID 22737251, 2012). "We conclude that LCN2 promotes tumor growth, invasion, angiogenesis, and maintains resistance to gemcitabine in insensitive lines." (PMID 23056397, 2012). "In this study, we examined the expression of LCN2 in precursor lesions of various grades and tumour tissue samples to correlate expression with the pathogenesis of PDAC." (PMID 23056397, 2012). "Lipocalin 2 (Lcn2), otherwise known as neutrophil gelatinase-associated lipocalin (NGAL), is upregulated in several solid cancers, and has been shown to facilitate tumor progression." (PMID 21649922, 2011). "Lipocalin 2 (Lcn2) was increased in all models but to a higher level in tumor-bearing mice, while platelet factor 4 (Pf4) was decreased in subacute inflammation but increased in chronic inflammation and cancer." (PMID 21589862, 2011). "For mouse assays, we assessed levels of Timp1 and Lcn2 in biological fluids and plasmas from tumor bearing mice (Stage I/II, n = 6; Stage III/IV, n = 5; controls, n = 18)." (PMID 19936259, 2009). "Until now, growing evidence suggests that lipocalin 2 plays an important role in innate immune response, cell apoptosis and tumor development." (PMID 19077278, 2008). "In our paper, the findings demonstrated that lipocalin 2 didn't affect the proliferation and anchorage-independent growth of 4T1 cells in vitro and primary tumor weight in vivo." (PMID 19077278, 2008). "But overexpression of lipocalin 2 in 4T1 cells didn't affect cell proliferation and anchorage-independent growth in vitro, and primary tumor weight in vivo." (PMID 19077278, 2008). "Based on the roles of lipocalin 2 in the migration and invasion of 4T1 cells we next examined the effects of lipocalin 2 on tumor formation and metastasis in vivo." (PMID 19077278, 2008). "As a transcription factor, E2F5 may participate in shaping the LSCC tumor microenvironment by directly or indirectly regulating the expression of NETs hallmark genes (e.g., S100A8/A9, LCN2), thereby influencing tumor progression." (PMID 41488283, 2026). "Lipocalin-2 (LCN2), also known as neutrophil gelatinase-associated lipocalin (NGAL), is a secreted glycoprotein involved in iron homeostasis and immune modulation, and it has emerged as a key mediator of tumor progression in various cancers." (PMID 40472740, 2025). "Importantly, inhibition of STAT3 (with SH4-54) and VEGF-A (with bevacizumab) partially reversed LCN2-driven tumor growth in BM-bearing mice." (PMID 41436606, 2025). "In turn, macrophages secrete IL-1β, which further upregulates LCN2 expression in tumor cells." (PMID 41436606, 2025). "Notably, tumor cells in the BM presented significantly higher LCN2 expression than their counterparts in primary tumors did." (PMID 41436606, 2025). "They showed that LCN2 expression is upregulated in tumor-infiltrating CD4+ T cells." (PMID 41303420, 2025). "In addition, LCN2 significantly suppresses tumor progression through inhibition of EMT and angiogenesis." (PMID 40109857, 2025). "Similarly, several reviews have revealed the associations of high levels of lipocalin 2 with poor prognosis in ER − /PR − /HER2 + tumors, and ER- and PR-negative status in tumor samples from patients with breast cancer, which is consistent with our study." (PMID 40450119, 2025).
tumor (continued). "Taken together, these findings suggest that LCN2 may regulate CRC metastasis by exerting bidirectional effects on both tumor cells and TME cells, and the LCN2/TGFB1/CXCL5 axis discovered in this study represents just a fraction of its complex involvement." (PMID 40313933, 2025). "Here, we review the tumor-promoting and tumor-suppressing roles of LCN2." (PMID 40109857, 2025). "To assess whether LCN2 regulates the ability of tumor cells to infiltrate the brain parenchyma, we conducted migration and transmigration assays." (PMID 41436606, 2025). "Additionally, LCN2 binds to SLC22A17 on tumor cells themselves, activating JAK2/STAT3 and upregulating VEGF-A expression, thereby promoting tumor angiogenesis." (PMID 41436606, 2025). "Furthermore, tumor-secreted LCN2 can bind to SLC22A17 on tumor cells, activating JAK2/STAT3 signaling and promoting VEGF-A expression and release, which enhances tumor neovascularization." (PMID 41436606, 2025). "We did not observe any difference in fecal lipocalin-2 levels between groups, however, we further linked the reduced tumor burden to decreased Th17 cells in vivo." (PMID 39979287, 2025). "Macrophages in CSF can promote cancer cells producing lipocalin-2 (LCN2) for tumor growth." (PMID 40883281, 2025). "Our research group further revealed that when osteoblast-derived EVs are internalized by PCa cells, they induce the expression of SERPINA3 and LCN2, exerting tumor-suppressive effects while simultaneously promoting osteoblastic metastasis, supported by in vitro and in vivo models." (PMID 41465584, 2025). "Functionally, H3K18la facilitates tumor growth via enhanced expression of lipocalin 2 (LCN2)." (PMID 41152975, 2025). "In these cancers, LCN2 has oncogenic effects, promoting tumor progression." (PMID 40109857, 2025). "Indeed, potential therapeutic agents that inhibit LCN2 function show anti-tumor potential and inhibit invasion." (PMID 40356520, 2025). "LCN2 defects increase tumor multiplicity, indicating that LCN2 is a tumor suppressor." (PMID 40109857, 2025). "In favor of this, preclinical models involving inhibition of CCL2, NOS2, and LCN2 pathways have shown anti-tumor effects and may be explored to improve IL6 inhibitory strategies after PD-L1 treatment failure." (PMID 39663510, 2025). "Most studies revealed that LCN2 is responsible for facilitating tumor progression and metastasis." (PMID 40313933, 2025). "The function of LCN2 depends on whether it is iron bound; that is, iron-loaded LCN2 promotes tumor growth and progression, whereas iron-free LCN2 has anti-tumor activity." (PMID 40109379, 2025). "Manipulation of EMT and iron transportation by LCN2 can also suppressive tumor progression." (PMID 40109857, 2025). "The ability of LCN2 to promote invasion has been ascribed to the ability of LCN2 to promote epithelial–mesenchymal transition and to promote angiogenesis, suggesting that LCN2 could be a potential therapeutic target in multiple tumor types." (PMID 40356520, 2025). "On the other hand, LCN2 is also capable of suppressing EMT to reduce tumor metastasis." (PMID 40109857, 2025). "LCN2 is dysregulated in a variety of cell types, including tumor cells." (PMID 40109857, 2025). "Additionally, immunohistochemistry (IHC) revealed lower LCN2 expression in metastatic tumor cells within MLNs than in the paired PTs, suggesting that GC cells with lower LCN2 expression are more likely to metastasize to LNs." (PMID 40884261, 2025). "Furthermore, the levels of angiogenesis‐related factors in tumour tissues varied based on LCN2 expression." (PMID 41363723, 2025). "In addition, upregulation of LCN2 inhibits the phosphorylation of focal adhesion kinase, impairing tumor cell adhesion and invasion." (PMID 40109857, 2025). "Interestingly, the serum LCN2 concentration decreases as tumor cells express estrogen and progesterone receptors, and higher levels of LCN2 correlate with an ER-negative status." (PMID 40450119, 2025).